SNORD115-33 (small nucleolar RNA, C/D box 115-33)
Synonyms: HBII-52-33
Gene: Small nucleolar RNA gene on chromosome 15 (25,230,838 to 25,230,919, forward strand). Ensembl gene ENSG00000200593.
Gene Ontology:
Biological process: RNA processing
Cellular component: nucleolus
Homologues: Orthologues: chimpanzee SNORD115 (99% identical), dog SNORD115 (61% identical). Paralogues in human: SNORD115-44 (98% identical), SNORD115-11 (96% identical), SNORD115-29 (96% identical), SNORD115-36 (96% identical), SNORD115-43 (96% identical), SNORD115-12 (95% identical), SNORD115-16 (95% identical), SNORD115-22 (95% identical), SNORD115-26 (95% identical), SNORD115-39 (95% identical), SNORD115-6 (95% identical), SNORD115-9 (95% identical), and 37 more.